EGFR (epidermal growth factor receptor)
Diseases named in the same sentence as EGFR in open-access papers (continued):
Sharing a sentence is not in itself a finding about the gene and the disease.
tumor (continued). "Nevertheless one of two responders was in a patient harboring a KRASG12C mutation in their tumor similar to our EGFR/HER dependent cells." (PMID 25992771, 2015). "In more than half of patients, tumor cells at the time of progression harbor a second-site T790M mutation, which confers resistance to EGFR TKIs." (PMID 26517520, 2015). "In patients whose tumor harbors a sensitizing EGFR mutation, systemic response rates to therapy with gefitinib or erlotinib range from 60–90%." (PMID 25784657, 2015). "The historical standard for EGFR mutation testing has been direct sequencing of DNA extracted from samples of resected tumor or from biopsies." (PMID 25591975, 2015). "EGFR mutation analysis is performed on tumor cells in biopsy or cytology specimens obtained from bronchoscopy, computed tomography- (CT-) guided biopsy, surgical resection, or drainage from malignant pleural effusions." (PMID 26448936, 2015). "EGFR promotes epithelial cell proliferation whereas up-regulated EGFR is linked to hyperplasia or neoplasia in lung epithelium." (PMID 26447616, 2015). "Postprogression tumor specimens were prospectively collected for T790M mutation analysis in 70 NSCLC patients with acquired resistance to initial EGFR TKIs." (PMID 25699082, 2015). "In the present study, peritumoral Cbl and EGFR expression were associated with tumor recurrence and survival, however, the role of intratumoral Cbl and EGFR on HCC recurrence and survivability was weakened after hepatectomy." (PMID 26474280, 2015). "One possible reason for the loss of EGFR amplification in vitro in addition to the growth pattern in vitro (adherent versus spheroid) is the propagation of tumor-derived cells in the presence of exogenous mitogens, especially EGF." (PMID 26136784, 2015). "Our results indicate that the loss of CMTM7 in NSCLC cells positively regulates EGFR signaling by decreasing Rab5 activation, thereby promoting tumor growth and migration." (PMID 26528697, 2015). "A follow-up study confirmed that EGFR mutation is the strongest predictive biomarker for progression-free survival and tumor response to first-line gefitinib versus carboplatin and paclitaxel." (PMID 26220301, 2015). "EGFR-mutated tumors showed a significantly higher necrosis/contrast enhancing ratio (p = 0.05) and a significantly lower contrast enhancing/tumor bulk ratio (p = 0.008)." (PMID 26337765, 2015). "The phosphoproteomic results suggested that in Smarcb1 deficient tumor cells phosphorylation of ErbB signaling cascade and EGFR itself persists even upon serum withdrawal." (PMID 26370283, 2015). "Dissemination outside the primary tumour site was observed in the xenografts containing activating EGFR mutations." (PMID 25969993, 2015). "The low EGFR mutation rate (5%) was insufficient to establish the cost-effectiveness of erlotinib for poor performance patients whose tumours are EGFR mutation +ve." (PMID 26137881, 2015). "Analysis of EGFR mutations in circulating tumor cells (CTCs) is feasible, and CTCs represent a promising material to predict EGFR-TKI-treatment efficacy and resistance." (PMID 26227959, 2015). "Circulating cell-free tumor DNA (ctDNA) has a high degree of specificity to detect EGFR mutations in NSCLC." (PMID 26227959, 2015).
tumor (continued). "Missing data on EGFR mutational status largely resulted from unavailable tumor samples or because the trials were conducted before widespread testing." (PMID 25547901, 2015). "Destabilization of equilibrium between the active and inactive state of EGFR kinase activity toward promoting enzyme activation is a result of these mutations which in turn causes EGFR to translate into tumor growth and gives a survival advantage." (PMID 26041145, 2015). "A prognostic effect was found for PD-1-positive tumor infiltrating lymphocytes in patients with non EGFR-mutated tumors (p = 0.018)." (PMID 26313362, 2015). "EGFR mutations analyzed from peripheral blood samples correlated with DNA analysis from matched tumor tissue; however ctDNA had a greater sensitivity for detecting EGFR mutations than DNA extracted from CTCs." (PMID 26603430, 2015). "Circulating cell-free tumor DNA (ctDNA), which is released from tumor cells to circulating blood, can be applied to detect EGFR mutations in NSCLC patients." (PMID 26227959, 2015). "After the treatment, patients with a tumor exhibiting EGFR mutation had a median OS of 17 months compared to 10 months in patients whose tumors were without an EGFR mutation (p = 0.098)." (PMID 26392415, 2015). "The anti-tumor effect against EGFR-mutant tumors including T790M mutation was confirmed in mouse models without any significant toxicity." (PMID 26090892, 2015). "In 37 advanced NSCLC patients harboring activating EGFR mutations in tumor tissues, 31 cases were identified to have the EGFR mutations in CTCs." (PMID 26227959, 2015). "Western blot analysis for an additional auto-phosphorylation site of the EGFR, residue Y1092, showed higher levels of phosphorylation in Smarcb1 deficient tumor cells compared with Smarcb1 proficient cells under low serum." (PMID 26370283, 2015). "QIAGEN’s circulating tumour plasma DNA test for EGFR mutations in NSCLC received CE-IVD status in January 2015." (PMID 26101870, 2015). "The extent of ERK1/2 activation for example correlated with aggressiveness of NSCLC tumours and was associated with poor prognosis in patients and constitutive EGFR-mediated signaling is usually associated with poor prognosis of many human malignancies." (PMID 25674792, 2015). "Their main purposes were to compare ctDNA with tumor tissues in terms of its diagnostic accuracy for the detection of EGFR mutations." (PMID 26227959, 2015). "In lung ASC, the frequency of EGFR mutations was reported to be 33.3% in tumor specimens and which were significantly more frequent in women than men (44.4% vs. 25%) and in never-smokers than smokers (40% vs. 16.7%)." (PMID 26445240, 2015). "Lewis y antigen (a double-fucosylated oligosaccharide, located at the ends of many glycoproteins and glycolipids as a tumor-associated carbohydrate antigen) is part of the EGFR structure." (PMID 26539494, 2015). "Mutation analysis revealed that the tumor expressed the wild type epidermal growth factor receptor (EGFR) gene." (PMID 25899913, 2015). "Several groups have detected EGFR gene mutations in DNA isolated from plasma or serum samples, which serve as substitutes for tumor tissue; some groups have demonstrated a correlation between mutation status in the plasma/serum and tumor tissue." (PMID 26047516, 2015). "Inhibition of EGFR signaling with Gefitinib or Lapatinib reduced proliferation of Smarcb1 deficient tumor cells as demonstrated by a WST1 proliferation assay." (PMID 26370283, 2015). "Although overproliferation would make a (malignant) cell vulnerable to stresses resulting in programmed cell death and eventual tumor regression, mutations in this pathway (EGFR pathway) can bypass this by developing survival adaptation." (PMID 25711830, 2015).
tumor (continued). "In conclusion, the present study verified that the expression of EGFR was highly correlated with CD31, CD146 and HIF-1α in human AdCC and also suggested a possible association between EGFR and tumor-derived angiogenesis in this tumor." (PMID 25997612, 2015). "In NSCLC tumours, recurrent EGFR mutations are localized within the catalytic domain and comprise both INDELs and point mutations." (PMID 25874976, 2015). "On the other hand, ~30% patients with TKI-sensitive EGFR mutations fail to demonstrate objective tumor regression on initial EGFR-TKI therapy and are defined as having primary or intrinsic resistance." (PMID 25823662, 2015). "Currently, KRAS and BRAF mutations are routinely tested in tumor tissue by various methods for selection of anti-EGFR therapy in metastatic CRC patients." (PMID 26452027, 2015). "A multivariate analysis revealed EGFR as a significant prognostic marker and a risk factor for tumor recurrence in intrahepatic CC." (PMID 26729094, 2015). "Additional studies of these strategies to combat or prevent the development of central nervous system disease in patients with initial sensitizing mutations in their tumor EGFR should be considered." (PMID 25784657, 2015). "Nowadays, tumor tissues acquired by surgery or biopsy are the routine materials for EGFR mutation analysis." (PMID 26227959, 2015). "Future studies are required to clarify the biological features of these tumours and investigate the mechanisms underlying the primary resistance to EGFR-TKIs when the EML4-ALK rearrangement is present." (PMID 25788996, 2015). "Studies of the role of EGFR in organ and tissue development have been nearly overshadowed by the discovery of the role of activating EGFR mutations in tumor biology." (PMID 26436111, 2015). "Given our concern for the high risk of recurrence, the patient's primary tumor was tested and noted to be epidermal growth factor receptor (EGFR) positive." (PMID 26294988, 2015). "EGFR overexpression was found as an independent prognostic factor for survival and a risk factor for tumor recurrence after resection in intrahepatic CCA and, associated with tumor progression and invasion in extrahepatic CCA." (PMID 26571380, 2015). "Patients who responded to erlotinib treatment in the current study exhibited a rapid reduction of tumor size, as was the case for EGFR mutation-positive NSCLC." (PMID 25364452, 2014). "In all three samples, EGFR mutations were detected in diagnostic tumour specimens using the Sequenom massarray using standard iPlex chemistry." (PMID 24999991, 2014). "Compensatory mutations in the tyrosine kinase domain of EGFR or the constitutively active and truncated form of EGFR (i.e. EGFRvIII) are shown to predict response to anti-EGFR therapy in other tumor types." (PMID 24899223, 2014). "It inhibits the intracellular phosphorylation of tyrosine kinase associated with the EGFR to restrain the development of the tumor." (PMID 25000529, 2014). "Since EGFR and Notch inhibitors are already developed as therapeutic agents in diverse tumour models, these targets and associated pathways will create the basis for the development of new therapeutic control in E-cadherin-mediated cancer." (PMID 24978478, 2014). "2- Concordant EGFR mutation status was found within the tumor, and between primary and thoracic metastasis." (PMID 24885034, 2014). "GBM-associated tumor antigens including EGFR, HER2, TRP2, MRP3, AIM2, and SOX2 were twofold to >200-fold higher in CSCs than those in adherent cells." (PMID 25126583, 2014). "Overexpression of EGFR promotes gene amplification and mutation consequence in cell proliferation, survival, invasion, metastasis, and tumor induced neoangiogenesis." (PMID 24723942, 2014).
tumor (continued). "It is highly recommended that all patients with mCRC who are candidates for anti-EGFR monoclonal antibody therapy have their tumours tested for KRAS mutation." (PMID 25361007, 2014). "At the opposite, among the mutated specimens with low tumor cell content 4 /18 had a CN ≥ 2.5 suggesting that EGFR CN impacts on mutation detection for low tumor cell content specimens." (PMID 24885034, 2014). "The tumor-specific variant of the epidermal growth factor receptor, EGFRvIII, is a type III in-frame deletion mutant of the wild-type receptor that is exclusively expressed on the cell surface of GBMs and other neoplasms but is absent on normal tissues." (PMID 24722266, 2014). "It validates the accuracy of EGFR mutation screening from single tumor-biopsy samples before first line EGFR-TKI." (PMID 24885034, 2014). "For selected NSCLC groups according to gender, smoking status, tumor stage, or EGFR mutation, the incidence of ALK rearrangements ranged from 4.30% to 34.78% based on 20 articles (15 in East Asians; 3 in Caucasians; 2 in multi-ethnic groups)." (PMID 24959902, 2014). "A likely explanation is that apart from the tumor cells with both sensitizing and T790M EGFR mutations, some of the patients had residual amounts of tumor cells that only possessed the sensitizing mutation." (PMID 25103305, 2014). "The two major mechanisms for the development of resistance during treatment are the occurrence of tumour cell clones which carry additional EGFR mutations or additional genetic alterations that can co-occur with EGFR-activating mutations." (PMID 24643470, 2014). "Gene amplification and some additional type of mutations all cause overexpression of EGFR protein in the tumor cells." (PMID 25330173, 2014). "In phase II trials, patients were screened and stratified by EGFR mutation status with planned subgroup analysis by both EGFR mutation and pre-treatment tumor MET expression levels." (PMID 25221748, 2014). "Given this strong benefit of EGFR-TKIs in patients with a tumour with an EGFR activating mutation (EGFR mut + tumour), molecular profiling became necessary in the assessment of stage IV NSCLC." (PMID 25264519, 2014). "The present study was devised to evaluate the correlation between EGFR mutation status in basal tumor biopsies and matching circulating tumor cells of NSCLC patients." (PMID 25137181, 2014). "An association between EGFR expression and tumor grade was shown when evaluation was performed with 31G7 using scoring method (B) (p = 0.02) and 2.1E1 employing scoring method (A) (p = 0.009) and (C) (p = 0.047)." (PMID 25227424, 2014). "In the first year the curve of cumulative incidence of BM in EGFR mutated patients rises slower than in EGFR wild type, yet after one year the curves of EGFR mutant and EGFR wild type tumours overlap." (PMID 24991207, 2014). "Of 1200 patients, 437 had a tumor specimen that was evaluable for EGFR mutation analysis and of these, 261 patients (59.7%) had tumors that contained EGFR gene mutations." (PMID 25309870, 2014). "It should be noted that overexpression of EGFR occurs in a wide range of human tumour tissues and, as with a reduced p27Kip1, is strongly associated with late-stage tumours and poor prognosis." (PMID 25121353, 2014). "In samples with various tumor cell contents and various EGFR gene copy number the quantification of the mutated allele/wild type allele ratio is difficult." (PMID 24885034, 2014). "Based on these results, we investigated the relationship between tumor progression and amount of EGFR mutations, T790M and/or L858R, with plasma DNA." (PMID 25462870, 2014). "In the preclinical setting, this is well exemplified by the inactivity of EGFR-TKIs in H1650 cells or tumours (NSCLC) that harbour a Del 19 EGFR mutation and are at the same time PTEN-mutated." (PMID 24643470, 2014).
tumor (continued). "In such a case, although she died of progressive disease of T790M mutated tumor cells in her thorax, EGFR-TKI, which was effective in the brain metastases, was beneficial for her to improve her quality of life." (PMID 24555578, 2014). "We used an ultra-sensitive mass spectrometry based system to highlight the presence of an EGFR-activating mutation in both isolated CTCs and plasma cell-free DNA (cf-DNA), and demonstrate concordance with the original tumor-biopsy samples." (PMID 24999991, 2014). "Tumor volumes of primary and metastatic lesions, as well as EGFR mutation status using plasma DNA, were evaluated monthly from one to four months after inoculation with H1975 cells." (PMID 25462870, 2014). "Recently, several large, controlled, phase III studies have been published in NSCLC patients with EGFR mutation-positive tumours." (PMID 25100284, 2014). "An activating mutation on the gene encoding for EGFR leads to an upregulation of the EGFR, which results in uncontrolled proliferation of tumor-cells, using the tyrosine kinase pathway." (PMID 25538894, 2014). "Elevated EGFR and cMET expression levels correlate with tumor disease progression and are associated with increased tumor growth, cell migration and invasion." (PMID 24638075, 2014). "One of the defined mechanisms is that EGFR amplification or Ras activation by mutations results in increased clonogenic cell survival and decreased tumor growth delay following irradiation." (PMID 25302298, 2014). "The biological activity was associated with the potential difference in tumor sensitivity of EGFR TKIs." (PMID 24533047, 2014). "In conclusion, we report for the first time that CTC preparations obtained by the CellSearch platform represent a suitable source of tumor DNA for an efficient detection of EGFR mutations by ultra-deep next generation sequencing." (PMID 25137181, 2014). "The first-line treatment for advanced non-small cell lung cancer (NSCLC) depends on the tumor histology and the presence of epidermal growth factor receptor (EGFR) mutation or anaplastic lymphoma kinase (ALK) rearrangements." (PMID 24748366, 2014). "Previous studies have shown that there is an association between the presence of EGFR gene amplification and the EGFR genetic variant III in GBM and other tumor types, being patients carrying both EGFR amplification and EGFRvIII those with a worse survival." (PMID 24352766, 2014). "Another study revealed that after tumor cells with EGFRL858R-sensitive mutation were treated with EGFR-TKI, T790M\PIK3A resistance mutation occurred." (PMID 25610713, 2014). "Therapeutic decisions in patients with metastatic NSCLC are guided by the EGFR mutation status, which is determined in tumor biopsies." (PMID 24465542, 2014). "Fifty-seven samples were EGFR mutated and 40 had adequate tumor specimens for analysis on multiple spatially separated sites." (PMID 24885034, 2014). "Of the 30 patients who had tumor tissue samples available for EGFR mutation analysis, 16 patients had EGFR activating mutations and 14 patients were EGFR wild-type." (PMID 24932312, 2014). "The anti-tumor effects of mAbs are restricted to only a fraction of patients, and also will disappear if the extracellular domain of EGFR becomes mutated during the genetic development of the tumor." (PMID 24801752, 2014). "Unfortunately, almost all patients will ultimately develop resistance to EGFR-TKI, in whom more than 50% cases were detected harboring the EGFR T790M mutation in tumor specimens after EGFR-TKI." (PMID 25405807, 2014). "A discordance of EGFR mutations in primary tumours and corresponding metastases has been reported as well as intratumoural heterogeneity." (PMID 24773774, 2014). "This initiative has led to the discovery of some key molecules and pathways including the vascular endothelial growth factor (VEGF) in tumor angiogenesis and the epidermal growth factor receptor (EGFR) with the therapy guiding KRAS/NRAS mutations." (PMID 25261368, 2014).